RNU6-677P (RNA, U6 small nuclear 677, pseudogene)
Gene: Small nuclear RNA gene on chromosome 9 (37,333,857 to 37,333,957, reverse strand). Ensembl gene ENSG00000252723.
Homologues: Orthologues: rabbit U6 (65% identical), rabbit U6 (50% identical). Paralogues in human: RNU6-28P (68% identical), RNU6-1067P (67% identical), RNU6-1124P (67% identical), RNU6-222P (67% identical), RNU6-737P (67% identical), RNU6-1296P (66% identical), RNU6-1318P (66% identical), RNU6-17P (66% identical), RNU6-18P (66% identical), RNU6-36P (66% identical), RNU6-865P (66% identical), RNU6-1 (65% identical), and 1282 more.